U2AF2 (U2 small nuclear RNA auxiliary factor 2)
Diseases named in the same sentence as U2AF2 in open-access papers (continued):
Sharing a sentence is not in itself a finding about the gene and the disease.
metastatic melanoma (1 paper, 2021). A melanoma that has spread from its primary site to another anatomic site. "Moreover, high mRNA levels of ILF2 and U2AF2 were associated with poor outcomes in metastatic melanoma patients." (PMID 34709752, 2021). "Consistently, we observed that both ILF2 and U2AF2 proteins showed nuclear localisation in metastatic melanoma cell lines." (PMID 34709752, 2021). "In summary, ILF2 forms a complex with U2AF2 to promote cell proliferation and colony formation in metastatic melanoma." (PMID 34709752, 2021). "Higher ILF2/U2AF2 expression and a consequently significantly higher expression of RAD50 were observed in metastatic melanoma tissues compared to primary tissues." (PMID 34709752, 2021). "Our results show that ILF2 and U2AF2 may have implications in RAD50 and ATM mRNA processing in metastatic melanoma." (PMID 34709752, 2021).
multiple myeloma (1 paper, 2021). "Another study showed that ILF2/YB‐1/U2AF2 complex promotes DDR‐related mRNA processing that affects the expression of FANCD2 and EXO1 in multiple myeloma." (PMID 34709752, 2021).
osteosarcoma (1 paper, 2019). A usually aggressive malignant bone-forming mesenchymal neoplasm, predominantly affecting adolescents and young adults. "A recent unbiased proteomic approach in human osteosarcoma, revealed PANDA interacts with SAFA and other splicing factors like U2 small nuclear RNA auxiliary factor 2 (U2AF65), polypyrimidine tract binding protein (PTBP1) and participates in alternative splicing." (PMID 31141943, 2019).
pulmonary hypertension (1 paper, 2025). Increased pressure within the pulmonary circulation due to lung or heart disorder. "Targeting regulatory noncoding RNAs can mitigate pathological splicing; in pulmonary hypertension, intervention against the super‐enhancer‐driven lncRNA HCG20 corrects its pathogenic splicing of EIF2AK2 by stabilization U2AF2." (PMID 41399527, 2025). "Similarly, in pulmonary hypertension, the super‐enhancer‐driven lncRNA HCG20 stabilizes U2AF2 and enforces pathogenic splice‐site usage, illustrating how a single dysregulated noncoding RNA can hijack the splicing machinery to drive disease progression." (PMID 41399527, 2025). "In pulmonary hypertension, the super‐enhancer‐driven lncRNA HCG20 binds and stabilizes U2AF2, promoting aberrant splicing of EIF2AK4 and contributing to endothelial dysfunction." (PMID 41399527, 2025).
Stroke (1 paper, 2024). Sudden impairment of blood flow to a part of the brain due to occlusion or rupture of an artery to the brain. "The stroke insult-related genes were Nfkb1, histone deacetylase 2 (Hdac2), and sirtuin 1 (Sirt1) in the vs. MCAO+tDCS-FN(cA) and U2 small nuclear RNA auxiliary factor 2 (U2af2) in the vs. MCAO+tDCS-FN(iC-cA) configurations." (PMID 38389833, 2024).
cancer (24 papers, 2012 to 2026). A tumor composed of atypical neoplastic, often pleomorphic cells that invade other tissues. "Future studies are needed to unravel the potential roles of recurrent U2AF2 mutations in the transformation of normal cells to cancers and to elucidate their genome-wide effects of splicing." (PMID 35406598, 2022). "Cancer-associated U2AF2 mutations mostly fall within the RRM1 motif, at the interface that interacts with nucleotides in the 3′ half of the PPT." (PMID 35406598, 2022). "Cancer mutations found in U2AF2 have been mapped to structural changes in RNA recognition motifs (RRMs) affecting the selection at the 30 splicing site (30SS)." (PMID 33597859, 2021). "Among them, the phosphorylated protein U2AF2 is a key protein in the signaling pathway of the spliceosome, and the important functional surface of its splice factor is also related to cancer-related mutations." (PMID 34437425, 2021). "Yet, the minimal U2AF1 UHM lacked the sites of MDS-associated mutations, which limited the smFRET investigations to relatively rare, cancer-associated mutations of U2AF2 (L187V and M144I)." (PMID 32343311, 2020). "Less frequently, the U2AF2 subunit acquires cancer-associated missense mutations, which tend to cluster at the U2AF2/RNA or inter-domain interfaces." (PMID 32343311, 2020). "Collectively, U2AF2 cancer-associated mutations falling within the two RRMs impact the equilibrium between the “closed” (unbound) and “open” (RNA binding-competent) conformations, alter binding of the protein to the PPT, and dysregulate pre-mRNA splicing, similarly to U2AF1 mutations." (PMID 35406598, 2022). "Cancer mutations found in U2AF2 were previously mapped to U2AF65 structures." (PMID 32664474, 2020). "U2AF2 mutations leading to spliceosome dysfunction have been reported in other cancers." (PMID 30867899, 2019). "Despite the major role of U2AF2 in pre-mRNA splicing, facilitating the recognition of exon-intron boundaries and identification of the 3′ splice site during the spliceosome assembly, until recently, U2AF2 passenger somatic variants have only been loosely linked to cancer." (PMID 37962958, 2024). "Small molecules targeting U2AF2 or other splicing factors have been actively pursued as potential treatments of splicing-related cancers." (PMID 41404809, 2025). "Our strategy to abrogate the growth of the U2AF1 mutant cancer cells is to target U2AF1-UHM that binds with U2AF2 to form a dimer recognizing the 3’ splice site in pre-mRNA splicing." (PMID 38883705, 2024). "Previous studies demonstrated the role of U2AF2 in alternative splicing, which can foster a variety of diseases, including cancer." (PMID 39402324, 2024). "Although a handful of isomiRs were dysregulated in our LIHC samples, there should be more oncogenic or tumor-suppressing isomiR candidates in other cancers in which RBPs, such as hnRNPC and U2AF2, are dysregulated." (PMID 35729324, 2022). "Albeit at lower frequency, cancer-related mutations were also identified in the U2AF2 gene, encoding the U2AF larger subunit U2AF65." (PMID 35406598, 2022). "U2AF2 and PUF60 mutations in cancer cells are less restricted than those in SF3B1 or U2AF1; nevertheless, a previous study mapped recurrent mutations to U2AF65-RNA interfaces." (PMID 32664474, 2020). "At least three RRM mutations increased skipping of internal U2AF2 (~9%, 2/23) or PUF60 (~8%, 1/13) exons, indicating that cancer-associated RRM mutations can have both cis- and trans-acting effects on splicing." (PMID 32664474, 2020). "Though less frequently found in cancers compared to U2AF1 mutations, U2AF2 mutations were recently identified to cause neurodevelopmental disorders (NDD) in patients presenting with overlapping cognition impairments, hypotonia, seizures, autistic features, and various behavioral disturbances." (PMID 41404809, 2025). "U2AF2 has been reported to act as an oncogene in several cancers." (PMID 32894165, 2020).
cancer (continued). "Among them, candidate proteins EEF2, U2AF2 and FLNC are significantly enriched in the three pathways of “spliceosome” (p-value: 1.01 × 10−3), “proteoglycans in cancer” (p-value: 8.58 × 10−2) and “focal adhesion” (p-value: 1.48 × 10−3)." (PMID 34437425, 2021). "These outcomes of TERT AS also matched our predictions that SRSF2 and U2AF2 were FL TERT promoters in cancer cells, while HNRNPM would not impact splicing of TERT exons 7/8." (PMID 37531400, 2023). "The clustering of mutations within conserved domains would support their importance in cancer initiation or progression and the role of U2AF2 or PUF60 as oncogenes as opposed to tumor suppressors." (PMID 32664474, 2020).
tumor (17 papers, 2006 to 2026). "SNRPD3 and U2AF2 showed (50%) the highest association; DDX5, DDX17, and SNRPF in between (40–50%) with neoplasm class." (PMID 34918006, 2022). "Subsequently, we found that U2AF2 expression in RCC tumor tissues was increased compared with normal healthy tissues." (PMID 34514002, 2021). "Immunohistochemistry was performed to detect the effects of the U2AF2/cARF1/miR-342–3p/ISL2 axis on tumor tissues." (PMID 32894165, 2020). "We also checked the expression of U2AF2 and RBFOX1, two other known factors implicated in neuronal ME splicing, by semi-quantitative PCR between the three tumor grades." (PMID 33207694, 2020). "We observed that Dnmt3aR878H/+Npm1cA/+ MDS/MPD was associated with mutations in the tumor suppressor Cux1, previously shown to drive MDS and MDS/MPD and in the RNA splicing genes Rbm10 and U2af2." (PMID 30692594, 2019). "Quantitative phosphoproteomics integrated with multiple bioinformatics analysis revealed a series of phosphopeptides and candidate proteins such as EEF2, U2AF2 and FLNC involved in tumor metastasis and invasion." (PMID 34437425, 2021). "Compared to the control group, the tumor volumes were enlarged in the ISL2 overexpression and U2AF2 overexpression groups, and decreased in the miR-342–3p-mimic and cARF1-knockdown groups." (PMID 32894165, 2020).
neurodevelopmental disorder (2 papers, 2021 to 2024). A behavioral and cognitive disorder with onset during the developmental period that involves impaired or aberrant development of intellectual, motor, or social functions. "Spliceosome defects involving U2AF2, PRPF19, and RBFOX1 variants contribute to neurodevelopmental disorders by disrupting neuritogenesis and brain development." (PMID 37962958, 2024).
neurological diseases (1 paper, 2021). "Similarly, the function of U2AF2 in neurological diseases has not been reported in the literature." (PMID 33597859, 2021).
U2AF2 also shares sentences with these, for which no sentence is quoted: colon cancer (3 papers); infection (3); chronic lymphocytic leukemia (2); cutaneous melanoma (2); colorectal tumor (1); Fanconi anemia (1); frontotemporal dementia (1); genetic diseases (1); hepatocellular carcinoma (1); liver cirrhosis (1); lymph node disease (1); malignant mesothelioma (1); Myelodysplasia (1); neurodegenerative disease (1); nevus (1); Obesity (1); osteoarthritis (1); Pancreatic Carcinoma (1); prion disease (1); psychiatric disorder (1); renal cell carcinoma (1); rheumatoid arthritis (1).